TYK2 (tyrosine kinase 2)
Diseases named in the same sentence as TYK2 in open-access papers (continued):
Sharing a sentence is not in itself a finding about the gene and the disease.
systemic lupus erythematosus (37 papers, 2011 to 2026). An autoimmune multi-organ disease typically associated with vasculopathy and autoantibody production. "TYK2 polymorphisms have been linked with autoimmune diseases such as systemic lupus erythematosus (SLE), psoriasis, and multiple sclerosis (MS)." (PMID 40410684, 2025). "Among them, the inhibition of TYK2 emerges as a promising therapeutic strategy due to its interference with key cytokines underlying lupus pathogenesis." (PMID 37457579, 2023). "Other pathways involved in lupus pathogenesis, such as tyrosine kinase 2 (TYK2) and serine/threonine kinase IL-1R–associated kinase (IRAK4), represent potential future therapeutic targets of interest." (PMID 35899214, 2022). "Genome wide association studies have linked a SNP (rs34536443) within TYK2 encoding a Proline to Alanine substitution at amino acid 1104, to protection from multiple autoimmune diseases including systemic lupus erythematosus (SLE) and multiple sclerosis (MS)." (PMID 30740104, 2019). "IL-23 inhibition and TYK2 inhibition appear to offer a balanced profile of efficacy and lupus-related safety in psoriatic disease complicated by lupus-spectrum autoimmunity." (PMID 41596733, 2026). "TYK2 is activated in response to cytokines actively involved in lupus pathogenesis; this review highlights the potential of targeting TYK2 as a promising therapy for SLE." (PMID 37457579, 2023). "As a consequence of this discovery, a TYK2 inhibitor is currently being trialled for use in treating patients with CD, systemic lupus erythematosus (SLE) and psoriasis (Ps), with promising initial results." (PMID 34508276, 2022). "Several SNPs within TYK2 are associated with autoimmune and inflammatory diseases, such as T1DM, RA (rheumatoid arthritis), SLE (systemic lupus erythematosus), MS (multiple sclerosis), and IBD (inflammatory bowel disease)." (PMID 32226409, 2020). "Thus, the repurposing potential of TYK2 inhibitors for systemic lupus erythematosus and rheumatoid arthritis identified by genetic evidence in our current study needs clinical validation in an RCT setting." (PMID 36842216, 2023). "Second, we show that the same three TYK2 variants protect against systemic lupus erythematosus (SLE, Pomnibus = 6x10-18), and provide suggestive evidence that two of the TYK2 variants (P1104A and A928V) may also protect against inflammatory bowel disease (IBD; Pomnibus = 0.005)." (PMID 25849893, 2015). "Several JAK inhibitors have been investigated in systemic lupus erythematosus, including baricitinib (JAK1/2 inhibitor), tofacitinib (JAK1/3 inhibitor), and the selective TYK2 inhibitor deucravacitinib." (PMID 41373894, 2025). "Increasing evidence for the efficacy of JAK inhibitors in other immune-mediated diseases and murine studies of lupus led to the first RCT of deucravacitinib, an oral, selective, allosteric TYK2 inhibitor, in SLE." (PMID 37457579, 2023). "In brief, these RCTs focused on examining the treatment effectiveness of TYK2 inhibitors on plaque psoriasis and a few studied ulcerative colitis, alopecia areata, systemic lupus erythematosus, atopic dermatitis, and active non-segmental vitiligo." (PMID 36842216, 2023). "Deucravacitinib (BMS-986165), a Tyk2 inhibitor that binds to the JAK homology 2 (JH2) domain, has been approved for treating psoriasis and reported to be effective in the treatment of systemic lupus erythematosus (SLE)." (PMID 39742289, 2024). "In addition, we also found that FNLS-YE1 could efficiently introduce protective alleles in TYK2 /WDFY4 and PCSK9/ANGPTL4, offering a potential approach to reduce susceptivity for systemic lupus erythematosus (SLE) and familial hypercholesterolemia (FH), respectively." (PMID 37285261, 2023).
plaque psoriasis (32 papers, 2022 to 2026). "The growing body of research on TYK2 inhibitors highlights their potential as a targeted immunomodulatory strategy, warranting clinical trials to assess their efficacy beyond plaque psoriasis." (PMID 41446689, 2026). "The novel TYK2 inhibitor deucravacitinib was recently approved by the FDA to treat patients with plaque psoriasis and is currently being tested in clinical trials for the treatment of other inflammatory disorders." (PMID 40991399, 2026). "In support of this, the first selective TYK2 inhibitor, deucravacitinib, is for the treatment of plaque psoriasis, with ongoing clinical trials in psoriatic arthritis, SLE, Crohn's disease, and ulcerative colitis." (PMID 40599891, 2025). "The findings reported here provide additional support that deucravacitinib, a once‐daily oral TYK2 inhibitor, is an efficacious and well‐tolerated therapeutic option for Japanese patients with moderate to severe plaque psoriasis." (PMID 40304108, 2025). "Deucravacitinib is an oral, selective, allosteric tyrosine kinase 2 inhibitor approved in the United States, European Union, South Korea, China, and other countries for the treatment of adults with moderate to severe plaque psoriasis." (PMID 40671612, 2025). "Selective inhibitors of TYK2, like Deucravacitinib, have gained approval for treating moderate-to-severe plaque psoriasis and are considered promising targets for multiple autoimmune conditions." (PMID 40075078, 2025). "Deucravacitinib is a novel, oral, selective, allosteric tyrosine kinase 2 inhibitor currently approved for the treatment of adults with moderate to severe plaque psoriasis." (PMID 40355364, 2025). "Janus kinase (JAK) inhibitors are immunosuppressive agents increasingly used in dermatology; among these, the tyrosine kinase 2 (TYK2) inhibitor deucravacitinib is approved for use in moderate-to-severe plaque psoriasis." (PMID 39507477, 2024). "Deucravacitinib, a TYK2 inhibitor, has proven to be a valuable addition to the growing array of treatments available for plaque psoriasis, demonstrating both efficacy and safety." (PMID 39430635, 2024). "With evidence from randomized controlled trials (RCTs), we aimed to perform a network meta-analysis (NMA) to assess the efficacy and safety of oral PDE4 and TYK2 inhibitors in treating moderate-to-severe plaque psoriasis." (PMID 37334353, 2023). "Evidence from RCTs confirmed the effectiveness of TYK2 inhibitors on plaque psoriasis and reported several adverse effects." (PMID 36842216, 2023). "In conclusion, this NMA has validated the potential of orally administered small-molecule drugs, including PDE4 and TYK2 inhibitors, in the treatment of moderate-to-severe plaque psoriasis." (PMID 37334353, 2023). "This has led to FDA approval of topical ruxolitinib (marketed as JAK1- and JAK2-selective) and oral preparations of abrocitinib and upadacitinib (both JAK1-selective) for AD, as well as oral deucravacitinib (TYK2-selective) for plaque psoriasis." (PMID 37298195, 2023). "Deucravacitinib is a selective TYK2 inhibitor that has been evaluated in plaque psoriasis and psoriatic arthritis with promising results." (PMID 35337068, 2022). "In conclusion, this analysis provides additional support that deucravacitinib, an oral, selective, allosteric TYK2 inhibitor, has an acceptable safety and tolerability profile and provides durable efficacy through 3 years in Japanese patients with plaque psoriasis." (PMID 40066907, 2025). "Deucravacitinib, an oral, selective, allosteric tyrosine kinase 2 inhibitor, was effective and well tolerated at a dose of 6 mg once daily through 1 year (52 weeks) in patients with moderate to severe plaque psoriasis in the phase 3 POETYK PSO‐1 and POETYK PSO‐4 trials." (PMID 40066907, 2025).
plaque psoriasis (continued). "POETYK PSO‐3, a 52‐week, double‐blind, phase 3 study, evaluated the efficacy and safety of deucravacitinib, an oral, selective, allosteric tyrosine kinase 2 inhibitor, in adult patients with moderate to severe plaque psoriasis in mainland China, Taiwan, and South Korea." (PMID 40671612, 2025). "In September 2022, the FDA-approved deucravacitinib, a first-in-class oral, selective, allosteric tyrosine kinase 2 (TYK2) inhibitor, after it demonstrated a favorable safety profile and greater efficacy than other available oral treatment options for plaque psoriasis." (PMID 40109802, 2025). "Therefore, the TYK-2 inhibitor deucravacitinib, approved in 2023 for the treatment of moderate to severe plaque psoriasis, was initiated." (PMID 40475785, 2025). "By selectively inhibiting TYK2, deucravacitinib disrupts these signaling pathways, mitigating keratinocyte hyperproliferation and excessive inflammation, making it an effective treatment for psoriasis vulgaris." (PMID 39830543, 2024). "Deucravacitinib is an oral medication for psoriasis vulgaris that selectively inhibits Tyk2." (PMID 39830543, 2024). "Additionally, oral deucravacitinib (TYK2-selective) was recently approved for the treatment of plaque psoriasis." (PMID 37298195, 2023). "Therefore, TYK2 inhibitors have demonstrated satisfactory performance in treating plaque psoriasis, warranting further development and more long-term, large-scale clinical trials for novel TYK2 inhibitors." (PMID 37334353, 2023). "Deucravacitinib, an oral, selective, allosteric TYK2 inhibitor, is approved in the United States, European Union, Japan, South Korea, China, and other countries for the treatment of adults with moderate to severe plaque psoriasis who are candidates for systemic therapy." (PMID 40304108, 2025). "Deucravacitinib is an oral TYK2 inhibitor that binds to the regulatory domain of TYK2 and is FDA-approved for moderate-to-severe plaque psoriasis." (PMID 41446689, 2026). "Other TYK2 inhibitors, such as lomedeucitinib and ESK-001, are currently in clinical development for plaque psoriasis." (PMID 41446689, 2026). "Deucravacitinib, a U.S. Food and Drug Administration-approved tyrosine kinase 2 (TYK2) inhibitor, has shown robust efficacy in Phase III trials for moderate-to-severe plaque psoriasis, with a favorable safety profile." (PMID 41011289, 2025). "IL-23 dominates in plaque psoriasis and plays a major role in modulating JAK2/TYK2 and STAT signaling, thereby increasing IL-17 production by immune cells." (PMID 40920623, 2025). "Deucravacitinib, a tyrosine kinase 2 (TYK2) inhibitor, was FDA-approved in 2022 for moderate to severe plaque psoriasis." (PMID 40004842, 2025). "Brepocitinib is an oral selective dual TYK2/JAK1 inhibitor and based on its cytokine inhibition profile is expected to provide therapeutic benefit in the treatment of plaque psoriasis." (PMID 38431923, 2024). "Deucravacitinib, a selective tyrosine kinase 2 (TYK2) inhibitor, has received approval in several countries for the treatment of moderate-to-severe plaque psoriasis." (PMID 39185023, 2024). "Recently, the first TYK2 inhibitor (i.e., deucravacitinib) was approved by the US Food and Drug Administration (FDA) for the treatment of moderate-to-severe plaque psoriasis." (PMID 38303723, 2024). "In 2023, another network meta-analysis, including 13 randomized clinical trials involving 5274 patients, compared the efficacy and safety of Tyk2 and PDE4 inhibitors in treating moderate to severe plaque psoriasis." (PMID 38399292, 2024). "Deucravacitinib, a selective inhibitor of tyrosine kinase 2 (TYK2), has been approved to treat moderate-to-severe plaque psoriasis." (PMID 36842216, 2023). "On 9 September 2022, deucravacitinib became the first oral Tyk2 inhibitor approved by the USA Food and Drug Administration (FDA) for the treatment of moderate to severe plaque psoriasis." (PMID 36834806, 2023).
plaque psoriasis (continued). "Deucravacitinib, an oral, selective TYK2 inhibitor, was granted approval by the FDA in 2022 for treating moderate-to-severe plaque psoriasis in adults." (PMID 37334353, 2023). "The objective of this study was to compare the efficacy and safety of oral small-molecule drugs, including TYK2 and PDE4 inhibitors, in treating moderate-to-severe plaque psoriasis." (PMID 37334353, 2023). "Orally administered small-molecule drugs including tyrosine kinase 2 (TYK2) inhibitors and phosphodiesterase 4 (PDE4) inhibitors are new candidates for systemic therapy in plaque psoriasis." (PMID 37334353, 2023). "A promising alternative, particularly for the treatment of plaque psoriasis, is deucravacitinib, a selective inhibitor of JAK family member TYK2." (PMID 35747941, 2022). "Deucravacitinib, a novel, selective inhibitor of TYK2 is currently under review at the FDA and EMA for treatment of moderate‐to‐severe plaque psoriasis." (PMID 35747941, 2022). "Series of TYK2 pseudokinase binders that selectively suppress TYK2-mediated signaling has been developed by Bristol Myers Squibb, which recently led to FDA-approval of deucravacitinib for the treatment of plaque psoriasis." (PMID 36678572, 2023). "Recently, oral deucravacitinib, a selective inhibitor of tyrosine kinase 2 (TYK2, a member of the JAK family), was shown to lead to larger improvements in symptom severity for patients with moderate‐to‐severe plaque psoriasis than oral Apremilast, the current standard of care." (PMID 35747941, 2022). "Brepocitinib (PF-06700841) is an oral selective dual TYK2/JAK1 inhibitor targeting signaling of multiple cytokines (IFN, IL-6, IL-12, IL-21, IL-22, and IL-23) and based on its cytokine inhibition profile is expected to provide therapeutic benefit in the treatment of plaque psoriasis." (PMID 38431923, 2024).
rheumatoid arthritis (31 papers, 2012 to 2026). A chronic, systemic autoimmune disorder characterized by inflammation in the synovial membranes and articular surfaces. "Moreover, mice harboring TYK2 polymorphisms show different susceptibilities to collagen-induced arthritis, thereby demonstrating that TYK2 deficiency leads to clinical rheumatoid arthritis." (PMID 37845748, 2023). "Systematic triangulation of trans-protein QTLs (pQTLs) with genetic and protein associations across many diseases highlights potential drug repurposing opportunities, e.g., tyrosine kinase 2 (TYK2) inhibitors for rheumatoid arthritis." (PMID 42097137, 2026). "Of the four subtypes of the JAK family (JAK1, JAK2, JAK3, and TYK2), JAK1 is involved in signaling through inflammatory cytokines such as IL-6, and it is known to cause lymphocyte activation and proliferation in rheumatoid arthritis (RA)." (PMID 39944226, 2025). "Tofacitinib is a JAK1/3 inhibitor, with less efficacy vs. JAK2 and TYK2, and it is approved for the treatment of rheumatoid arthritis, psoriatic arthritis and ulcerative colitis." (PMID 38665231, 2024). "Baricitinib is an inhibitor of JAK1/2, with moderate activity vs. TYK2, with an indication for the treatment of rheumatoid arthritis." (PMID 38665231, 2024). "Given the importance of Tyk2-dependent downstream cytokine signaling in this and other diseases such as rheumatoid arthritis and Crohn’s disease, Tyk2 inhibitors have the potential to be important therapeutics." (PMID 22995073, 2012). "TYK2 gene mutations are genetically linked to ankylosing spondylitis, psoriasis, Crohn’s disease, ulcerative colitis, type 1 diabetes, multiple sclerosis (MS), lupus erythematosus (SLE), and rheumatoid arthritis (RA)." (PMID 39726748, 2024). "Similarly, anti-TNFα therapy has been shown to reverse compromised Treg function in rheumatoid arthritis, and tyrosine kinase 2 (TYK2) inhibitors might prove superior to Janus kinase 1 (JAK1) inhibitors in the treatment of PsoA regarding Treg function." (PMID 40806470, 2025). "Specific JAK inhibitors, such as Filgotinib, Upadacitinib, and PF04965842, or TYK2 inhibitors and BMS-986165, are currently in clinical development for autoimmune diseases rheumatoid arthritis (RA), psoriasis, and Crohn’s disease." (PMID 34445373, 2021). "Given that type I IFN signaling utilizes JAK1 and tyrosine kinase 2 (TYK2) as signal transducers, JAK inhibitors—some of which are already approved for rheumatoid arthritis —show potential by blocking IFN-α and IFN-γ signaling, particularly in monocytes, as well as in other immune cells." (PMID 40181992, 2025).
inflammatory bowel disease (29 papers, 2015 to 2026). A spectrum of small and large bowel inflammatory diseases of unknown etiology. "previously revealed a Mendelian randomized association of TYK2 loss-of-function variants with hypothyroidism, inflammatory bowel disease, primary biliary cirrhosis, and type 1 diabetes." (PMID 38332917, 2023). "TYK2 is essential in JAK/TYK2 signaling of inflammatory bowel disease NOD2 is the first risk gene that has been identified for CD." (PMID 38046046, 2023). "There were Mendelian randomization associations of the TYK2 loss-of-function variant with hypothyroidism, inflammatory bowel disease, primary biliary cirrhosis, and type 1 diabetes." (PMID 36842216, 2023). "During experimental colitis, the ablation of IL-22/STAT3 signaling using tyrosine kinase 2 (TIK2) deficient mice exacerbates inflammatory bowel disease." (PMID 30235866, 2018). "MR associations of the TYK2 loss-of-function variant with hypothyroidism, inflammatory bowel disease, primary biliary cirrhosis, and type 1 diabetes supported further investigation of TYK2 inhibitors as a potential treatment for these diseases in future clinical trials." (PMID 36842216, 2023). "Tyrosine kinase 2 is a downstream intracellular mediator of interleukin-23 signaling, which has a key role in the pathogenesis of inflammatory bowel disease." (PMID 40355364, 2025). "This, together with the pathogenetic involvement of IL-12 and IL-13, provides the mechanistic bases for clinical research of Tyk2 inhibitors in the treatment of bowel inflammatory diseases." (PMID 36834806, 2023). "We identified a missense variant in TYK2, exhibiting a shared causal effect on FEV1/FVC and inflammatory bowel disease (rs12720356, PPLACO=1.38 × 10− 8)." (PMID 38102678, 2023). "Similarly, the TYK2 locus on chromosome 19 displayed an independent risk association shared across SLE, inflammatory bowel disease and T1D." (PMID 41317333, 2026). "Oral treatment with the selective TYK2 inhibitor, BMS‐986165 was also efficacious and ameliorated progression in murine models of spondylarthritis, lupus nephritis, inflammatory bowel disease, and autoimmune diabetes." (PMID 39835539, 2025). "Selective TYK2 inhibitors might benefit patients with PS, PsA, inflammatory bowel disease (IBD), and SLE." (PMID 37171669, 2023). "TYK2 is a key signaling kinase in the JAK-STAT pathway, particularly relevant to the pro-inflammatory receptors for cytokines such as IL-23, and is central to the pathogenesis of inflammatory bowel diseases, including UC." (PMID 40446056, 2025). "Tyrosine kinase 2 (TYK2) is an important immunomodulatory factor of innate and adaptive immune responses and is considered a drug target for selected autoimmune disorders and inflammatory bowel diseases." (PMID 39518103, 2024).